INHBA (inhibin subunit beta A)
Diseases named in the same sentence as INHBA in open-access papers (continued):
Sharing a sentence is not in itself a finding about the gene and the disease.
breast tumors (8 papers, 2015 to 2025). "In addition, we found that high expression of INHBA in breast tumor tissue was associated with the reduced survival of patients." (PMID 41008625, 2025). "These efforts led to the identification of INHBA, which appears to drive an aggressive tumor phenotype in basal subtype HER2+ cells and is associated with poor outcome in basal HER2+ breast tumors." (PMID 35248133, 2022). "Our findings suggest that INHBA plays a central role in conferring an aggressive phenotype to basal subtype HER2+ breast tumors." (PMID 35248133, 2022). "INHBA is upregulated in breast tumors and induces EMT, tumor growth and distant metastasis." (PMID 35611554, 2022). "Therefore, the development of therapeutic strategies using small molecule inhibitors against Activin receptors or neutralizing antibodies targeting Activin A ligand, could be used as an alternative approach for breast tumors overexpressing INHBA and/or IL13Rα2." (PMID 30805303, 2019). "This differential expression of the INHBA was not dependent on the category of breast tumors such as estrogen receptor, progesterone receptor, or Her2 status." (PMID 28721365, 2015).
lung carcinoma (8 papers, 2017 to 2025). "Furthermore, it was found that the growth of alveolar macrophages is associated with the proliferation of lung cancer cells, and under tumor-bearing conditions, they express high levels of INHBA." (PMID 41463203, 2025). "Additionally, INHBA (Inhibin—B-A), a gene associated with lung cancer progression, was upregulated, which may raise concerns about the potential carcinogenic effects of GLP-1 exposure on the lungs." (PMID 40843897, 2025). "Activin A secretion is induced in alveolar macrophages in lung cell carcinoma due to increased INHBA expression, and the use of activin A antagonists is found to inhibit the proliferation of malignant cells, suggesting that activin A supports lung cancer cell development." (PMID 41463203, 2025). "Of note, also the expression levels of other putative tumor-derived cachexia-inducing signaling compounds (OSM, LIF, TNFα, IFNγ, PTHrP, ZAG, PIF, TWEAK, IL-1β, MSTN and INHBA) were tested for possible correlation between expression level and prognosis for lung cancer patients." (PMID 28515477, 2017).
cervical cancer (7 papers, 2021 to 2025). A primary or metastatic malignant neoplasm involving the cervix. "Inhibin β-a, encoded with INHBA, is a member of the TGFβ superfamily and is a marker of reduced survival and poor prognosis in cervical cancer." (PMID 38397409, 2024). "Survival prognosis analysis indicated that higher INHBA expression was significantly associated with reduced Overall Survival (p = 0.001), disease Specific Survival (p = 0.006), and Progression Free Interval (p = 0.001) in cervical cancer and poorer prognosis in other tumors." (PMID 35058963, 2021). "In cervical cancer, INHBA overexpression was correlated with pathological features, antitumor immune response, and clinical prognosis." (PMID 40563693, 2025). "We also found that INHBA was highly overexpressed in most cancer types, including cervical cancer tissues, compared to that in adjacent normal tissues." (PMID 35058963, 2021). "In conclusion, we found that INHBA was overexpressed in cervical cancer and was significantly related to poor prognosis." (PMID 35058963, 2021). "While the role of INHBA has been comprehensively studied in many cancer types, its function in cervical cancer remains insufficiently understood." (PMID 35058963, 2021). "To identify the prognostic value of markers for cervical cancer, we evaluated the correlation between high expression of INHBA and patients’ survival time using Kaplan-Meier analysis with Cox regression, including OS, DSS, and PFI." (PMID 35058963, 2021). "We further confirmed that INHBA expression was higher in cervical cancer samples from GEO database and cervical cancer cell lines than in normal cervical cells." (PMID 35058963, 2021). "The results of the qRT-PCR analysis demonstrated that INHBA mRNA expression was higher in cervical cancer cell lines than in normal cervical epithelial cell lines." (PMID 35058963, 2021). "Next, we validated INHBA expression in cervical cancer using the Gene Expression Omnibus (GEO) database, including GSE7803, GSE63514, and GSE9750 datasets." (PMID 35058963, 2021). "However, a positive correlation was disclosed between INHBA expression and macrophage infiltration level in breast and cervical cancer." (PMID 38329386, 2024). "At present, it has been found that there is differential expression of INHBA in cervical cancer tissues, but whether it is related to the response of cervical cancer immune cells is unclear." (PMID 36984496, 2023). "The results demonstrated that higher INHBA expression was associated with poorer prognosis for OS (p = 0.001, HR = 2.30, 95% CI: 1.41–3.76), DSS (p = 0.006, HR = 2.18, 95% CI: 1.25–3.81), and PFI (p = 0.001, HR = 2.26, 95% CI: 1.39–3.67) in cervical cancer." (PMID 35058963, 2021). "In this study, we attempted to address the role of INHBA in cervical cancer for the first time." (PMID 35058963, 2021). "In addition, INHBA was upregulated in cervical cancer in GSE7803, GSE9750, and GSE63514 datasets." (PMID 35058963, 2021). "In our study, we found that high expression of INHBA correlated with poor OS, DSS, and PFI in cervical cancer patients." (PMID 35058963, 2021). "To further confirm our observations, we examined INHBA expression in cervical cancer lines, including SiHa and HeLa, compared to that in the normal epithelial cell line, END1, using qRT-PCR." (PMID 35058963, 2021). "Although it has been proven that INHBA is important for tumor development, no study has explored the precise function and mechanism of INHBA in cervical cancer." (PMID 35058963, 2021).
esophageal adenocarcinoma (7 papers, 2015 to 2025). A malignant tumor with glandular differentiation arising predominantly from Barrett mucosa in the lower third of the esophagus. "Analysis of 24 samples of normal squamous esophagus, Barrett's esophagus, and adenocarcinoma (n = 8 per group) for Activin A expression, encoded by the INHBA gene, showed a trending increase of expression during the progression to EAC (GDS1321)." (PMID 26447543, 2015). "In the context of malignancies, longer overall survival was seen in gastric and esophageal adenocarcinoma patients with higher expression of activin subunit inhibin beta A (INHBA)." (PMID 41463203, 2025). "A study on esophageal adenocarcinoma found higher INHBA expression in cancerous tissues compared to hyper-plastic esophageal tissues." (PMID 40426863, 2025). "When Activin signaling was inhibited with siRNA targeting the Activin A gene, INHBA, or with the Activin antagonist, Follistatin, esophageal adenocarcinoma cell lines demonstrated suppressed proliferation." (PMID 26447543, 2015). "This suggests that INHBA over-expression may enhance cell proliferation and be influenced by promoter demethylation and histone acetylation in esophageal adenocarcinoma cell lines." (PMID 40426863, 2025).
esophageal cancer (7 papers, 2010 to 2024). A primary or metastatic malignant neoplasm involving the esophagus. "This is consistent with previous reports suggesting that INHBA overexpression or increased Activin A plasma levels are associated with poor prognosis in lung, gastric, pancreatic and esophageal cancers." (PMID 30805303, 2019). "We performed gene set enrichment and SODEGIR analyses to identify enrichment in TREM1, PGC, INHBA, and AGR, all of which are involved in cancer-related pathways and associated with patient prognosis in esophageal carcinomas and premalignant Barrett’s epithelium." (PMID 39123475, 2024). "However, INHBA's increased expression levels in these patients' tumors more likely reflect its product's ability to homodimerize and form activin A, an FSH secretion activator and putative oncogene in esophageal carcinoma." (PMID 20174472, 2010).
lymph node metastasis (7 papers, 2011 to 2023). "Moreover, we found that INHBA up-regulation was associated with lymph node metastasis (N+) (odds ratio 5.6; 95% confidence interval 1.5 to 21.8; p-value = 0.012), as well as SERPINA3 down-regulation (odds ratio 4.0; 95% confidence interval 1.0 to 15.4; p-value = 0.044)." (PMID 21489260, 2011). "There were significant differences in FIGO staging, differentiation, lymph node metastasis and INHBA expression between patients with a good prognosis and poor prognosis (p < 0.05)." (PMID 36984496, 2023). "A significant difference was observed in FIGO staging, differentiation, lymph node metastasis and INHBA expression between patients with a good prognosis and poor prognosis (p < 0.05)." (PMID 36984496, 2023). "Furthermore, our analysis also demonstrated that INHBA was upregulated in patients with lymph node metastasis at N1, N2, and N3 stage." (PMID 34346300, 2021). "Furthermore, there was a significant positive correlation between the expression levels of INHBA mRNA and serum activin-A with lymph node metastasis and the progression of malignancy, respectively." (PMID 27835986, 2016). "In addition, we found that INHBA up-regulation and SERPINA3 down-regulation are significantly associated with lymph node metastasis." (PMID 21489260, 2011). "Expression of INHBA was closely correlated with Federation of Gynecology and Obstetrics (FIGO) staging, differentiation and lymph node metastasis (p < 0.05)." (PMID 36984496, 2023). "The expression of INHBA was closely related to tumor differentiation, TNM stage, lymph node metastasis, and overall survival in patients with CRC." (PMID 35236827, 2022). "The results indicated that the expression of INHBA protein was correlated with the histological differentiation (p = 0.0434), TNM stage (p = 0.0053), lymph node metastasis (p = 0.0262) and overall survival (p = 0.0383)." (PMID 35236827, 2022). "The expression level of INHBA was significantly higher in samples with the lymph node metastasis when compared to the samples showing no lymph node metastasis (N0 vs N2: P = 2.440900E-03)." (PMID 34346300, 2021). "The expression of INHBA was closely correlated with FIGO stage, differentiation and lymph node metastasis (p < 0.05), but not with age, tumor size, number of pregnancies, histological type and depth of invasion (p > 0.05)." (PMID 36984496, 2023).
nasopharyngeal carcinoma (5 papers, 2021 to 2024). A carcinoma arising from the nasopharyngeal epithelium. "Another possibility is the upregulating of SMAD2/3 by INHBA, as described in nasopharyngeal carcinoma and pancreatic ductal adenocarcinoma." (PMID 38329386, 2024). "INHBA silencing inhibited the proliferation of nasopharyngeal carcinoma cells and the invasion of SUNE1." (PMID 36984496, 2023). "Silencing INHBA also inhibited the proliferation and invasion ability of nasopharyngeal carcinoma SUNE1 cells in vitro." (PMID 34346300, 2021).
ovarian tumors (5 papers, 2020 to 2024). "To further assess this correlation between INHBA and genes associated with T cell function, we tested INHBA z score levels as extracted from cBioportal38, 39 for ovarian tumors against tumor immunophenotypes as defined from 9174 tumors of 29 solid cancers." (PMID 39248018, 2024). "However, inhibin-α knock-out mice that have increased INHBA and develop testicular and ovarian tumors, were shown to have reduced tumor formation when modified to overexpress INHBC." (PMID 36612143, 2022). "To accurately identify cell types that express INHBA in human and mouse ovarian tumors, we used in situ hybridization (ISH) with human and mouse INHBA probes, respectively." (PMID 38360876, 2024). "Furthermore, previous studies have shown that INHBA, which is homologous to INHBB in tumor cells, can partially mediate the activation of CAF in breast and ovarian tumor models." (PMID 37858201, 2023).
serous ovarian cancer (5 papers, 2019 to 2024). "“Jet set” probes, INHBA (204926_at) and INHBA (210511_s_at) were used to generate KM Curves of serous ovarian carcinoma, stratified by high and low INHBA expression." (PMID 39248018, 2024).
endometritis (4 papers, 2016 to 2021). An acute or chronic, usually bacterial infectious process affecting the endometrium. "Furthermore, except INHBA, all differentially expressed genes which are involved in immune system process were downregulated in cows affected by endometritis." (PMID 26965375, 2016). "The expression patterns of only 28 genes in subclinical endometritis have been substantially altered, of which 26 genes including PTHLH, INHBA, DAPL1, MAOB, CXCR4, and TGIF1 were identified in both subclinical and clinical endometritis." (PMID 33426032, 2020). "There are 92 genes, including PTHLH, INHBA, DAPL1, and SERPINA1, which were significantly highly regulated and 111 genes which had significantly poorly regulated expression levels, including MAOB, CXCR4, HSD11B, and BOLA, as recorded in clinical endometritis." (PMID 33426032, 2020).
gastric tumor (4 papers, 2021 to 2023). "INHBA was highly expressed and aberrantly methylated in gastric tumor samples, and high INHBA expression was associated with significantly poorer 5-year survival than low expression group." (PMID 33717664, 2021).
skin cancer (4 papers, 2016 to 2023). "Furthermore, fibroblasts that are activated by INHBA expression in keratinocytes of human papilloma virus-induced skin tumors have been shown to promote tumor cell migration, angiogenesis and an inflammatory response gene signature." (PMID 38304252, 2023). "To determine whether upregulation of activin expression occurs early during skin cancer development, we analyzed the expression of the activin βA subunit (INHBA) in biopsies of patients with histopathologically well‐characterized AK (Dataset EV1)." (PMID 27932444, 2017). "This is obviously not restricted to murine skin cancer, since our bioinformatics analysis revealed overexpression of INHBA in AK, together with various activin target genes in macrophages, which we had identified in our mouse model." (PMID 27932444, 2017).
bladder cancer (3 papers, 2021 to 2025). "Hypomethylation and increased expression of INHBA in bladder cancer were identified in the TCGA dataset using the UALCAN web portal." (PMID 35216189, 2022). "Kaplan–Meier analysis revealed the relationship between INHBA expression and survival in patients with bladder cancer." (PMID 35216189, 2022). "The expression levels of INHBA and SPHk1 were all markedly upregulated for bladder cancer both in vivo and in vitro." (PMID 34692520, 2021). "Knockdown of INHBA inhibited bladder cancer cell proliferation and migration in culture." (PMID 40144023, 2025). "We further explored whether INHBA expression was correlated with tumor stages, nodal metastasis status, histologic grade, histologic subtypes, and molecular subtypes in bladder cancer." (PMID 35216189, 2022). "Of particular interest, expression of INHBA and ACVR2B were increased in bladder cancer in both males and females, as compared to adjacent normal bladder tissue." (PMID 40144023, 2025). "In addition to INHBA, reported as the most upregulated gene in human bladder cancer, we also observed upregulation of ACVR2B in bladder cancer." (PMID 40144023, 2025). "INHBA expression was overexpressed in late tumor stages (T3–T4), high-grade, and non-papillary subtypes in bladder cancer." (PMID 35216189, 2022).
esophageal squamous cell carcinoma (3 papers, 2019 to 2025). Esophageal squamous cell carcinoma (ESCC) is a type of esophageal carcinoma (EC) that can affect any part of the esophagus, but is usually located in the upper or middle third. "In esophageal squamous cell carcinoma, high INHBA level predicts poorer prognosis." (PMID 31827640, 2019). "Furthermore, IGF2BP1 could promote inhibin subunit beta A (INHBA) expression level by stabilizing its mRNA, thereby triggering the activation of the INHBA/Smad2/3 signaling pathway, and eventually promoting the migration and invasion capacities of esophageal squamous cell carcinoma cells." (PMID 40584294, 2025).
invasive breast carcinoma (3 papers, 2021 to 2023). A carcinoma that infiltrates the breast parenchyma. "Of interest, INHBA was involved in the progression of ductal carcinoma in situ to invasive breast cancer." (PMID 36304286, 2022). "Next, we further confirmed the INHBA overexpression in two sub-types of BC, invasive breast carcinoma and invasive ductal breast carcinoma, using Oncomine database." (PMID 34346300, 2021). "Thus, we analyzed the correlations of INHBA expression with immune infiltration levels in BRCA (breast invasive carcinoma) and the subtypes (BRCA-Basal, BRCA-Her2, BRCA-LumA, and BRCA-LumB) by TIMER2.0." (PMID 36304286, 2022). "Besides, in invasive breast cancer tissues, INHBA mRNA was significantly elevated." (PMID 37644505, 2023). "In addition, we found that INHBA mRNA was frequently overexpressed in ESCC and invasive breast cancer." (PMID 37644505, 2023).
pulmonary hypertension (3 papers, 2021 to 2023). Increased pressure within the pulmonary circulation due to lung or heart disorder. "Then, in experimental models, they observed that in the condition of hypoxia, INHBA overexpression, driven by VE-cadherin promoter (VEcad-INHBA-Tg), resulted in exacerbated pulmonary hypertension, accompanied by deteriorated right ventricular hypertrophy." (PMID 34440838, 2021). "When pulmonary hypertension was induced by three weeks of exposure to 10% hypoxia, VEcad-INHBA-Tg mice exhibited exacerbated pulmonary hypertension, accompanied by deteriorated right ventricular hypertrophy compared to WT mice." (PMID 33741934, 2021). "While INHBA was initially found in gonadal cells, multiple studies show that it is a multifunctional cytokine with potent antiangiogenic effects in various disease states from cancer, asthma, and pulmonary hypertension." (PMID 37097749, 2023). "Notably, pulmonary hypertension was ameliorated, accompanied by less right heart hypertrophy in INHBA-ECKO mice compared to INHBA-flox mice after chronic exposure to hypoxia." (PMID 33741934, 2021). "However, EC-specific transgenic overexpression of INHBA in mice predisposed then to the development of pulmonary hypertension without apparent differences in the lung vessel density in neonates or adults." (PMID 37097749, 2023).
acne (2 papers, 2024). An inflammatory process of the sebaceous glands which is characterized by comedones, nodules, papules and/or pustules on the skin. "Moreover, the function of the other genes, including FAS, SDC1, ANGPTL2, IL-15RA, INHBA, and OSMR in lymphocytes, keratinocytes, fibroblasts, and smooth muscle, are yet to be explored, suggesting that acne involves not only the skin’s surface but also a wider systemic dysregulation." (PMID 38854033, 2024).
diabetes (2 papers, 2023 to 2024). "Taken together, a miR-130b/INHBA signaling axis may provide therapeutic targets for patients with PAD and diabetes at risk of developing CLI." (PMID 37097749, 2023).
heart failure (2 papers, 2017 to 2020). Inability of the heart to pump blood at an adequate rate to meet tissue metabolic requirements. "The mRNA expression of INHBA/ACTIVIN A, as well as serum INHBA/ACTIVIN A levels are positively correlated with heart failure, and hypertension in the elderly." (PMID 31884871, 2020).
hepatocellular carcinoma (2 papers, 2019 to 2023). A malignant tumor that arises from hepatocytes. "Intriguingly, its relationship with exosomes has also been investigated, indicating that TRIB3 could mediate the impairment of autophagy and facilitate the secretion of INHBA/Activin A-enriched exosomes of hepatocellular carcinoma, thus resulting in the occurrence of liver fibrosis." (PMID 37153569, 2023).